HTRA1 (HtrA serine peptidase 1)
Diseases named in the same sentence as HTRA1 in open-access papers (continued):
Sharing a sentence is not in itself a finding about the gene and the disease.
Stroke (continued). "In this population-based cohort study of 454 756 individuals, NOTCH3, HTRA1, and COL4A1/2 variants causing monogenic cSVD were associated with increased stroke and dementia risk." (PMID 36300346, 2022). "To date, little is yet known about the epigenetic impact of HTRA1 on the initiation and progression of vascular disorders including stroke." (PMID 36581876, 2022). "The prospective data further disclosed that the changed HTRA1 methylation was detectable 2 years preclinical of stroke and became more pronounced 1.5 years and 1 year before the clinical determination of stroke." (PMID 36581876, 2022). "In conclusion, this study revealed a significant correlation between altered HTRA1 methylation and stroke in preclinic, thus suggesting the potential of blood-based DNA methylation for the risk evaluation and even prevention of stroke." (PMID 36581876, 2022). "Genetic variants of ULK4, CAV2, HTRA1 and KLF12 are all associated with increased risk of stroke and the orthologous genes were upregulated in brain art ECs in obesity." (PMID 36400935, 2022). "NOTCH3, HTRA1, and COL4A1/2 pathogenic variants in monogenic stroke; Framingham cardiovascular risk; and ischemic stroke polygenic risk." (PMID 36300346, 2022). "We observed stroke-related altered HTRA1 methylation and expression in both case–control study and prospective study." (PMID 36581876, 2022). "In our study, the stroke-related altered HTRA1 methylation in blood cells was observed in both hospital-based case–control study and prospective nested case–control study." (PMID 36581876, 2022). "All these evidences suggest that HTRA1 participates in the pathogenesis of stroke by regulating angiogenesis via TGF-β signaling." (PMID 33746601, 2021). "Rare monogenic causes of stroke, such as mutations in NOTCH3 (linked to CADASIL), COL4A1, or HTRA1, may also be found with genetic testing." (PMID 40863347, 2025). "Rare and common variants at HTRA1 have been associated with larger WMH volume and increased stroke risk in the general population, with recent findings suggesting loss-of-function mechanisms through both reduced HTRA1 expression and lower serine protease enzyme activity." (PMID 39011113, 2024). "Our findings demonstrate a central role of HTRA1 for human disease including stroke and coronary artery disease and identify two independent mechanisms that might qualify as targets for future therapeutic interventions." (PMID 37986915, 2023). "Since the onset time of stroke may have an effect on the methylation levels of HTRA1, we further performed analyses comparing controls and stroke cases stratified by time of stroke onset in the prospective nested case–control study." (PMID 36581876, 2022). "The prospective results suggested that the methylation level of HTRA1 in blood DNA might be a preclinical marker for stroke." (PMID 36581876, 2022). "HTRA1 variants were associated with incident stroke (HR, 1.80; 95% CI, 1.05-2.86; P = .03) but not with vascular dementia (HR, 3.08; 95% CI, 0.87-7.55; P = .08)." (PMID 36300346, 2022). "The association between HTRA1 methylation and stroke in the case–control study was not completely consistent with the prospective nested case–control study when each CpG was considered." (PMID 36581876, 2022). "Cardiovascular risk burden was associated with increased stroke risk in NOTCH3 and HTRA1 carriers." (PMID 36300346, 2022). "However, hereditary stroke attributable to HTRA1 gene constitutes only a small proportion of all strokes." (PMID 36581876, 2022). "Notably, the combination of HTRA1 methylation and stroke-related variables had robust power to distinguish stroke cases with onset time ≤ 1 year from controls (AUC = 0.76, 95% CI 0.67–0.84)." (PMID 36581876, 2022). "Moreover, significantly decreased expression of HTRA1 was observed in the stroke cases, as well as in the preclinical stroke cases, indicating that the increased HTRA1 methylation in blood cells might be biologically meaningful." (PMID 36581876, 2022).
Stroke (continued). "These loci provide insights into lacunar stroke pathogenesis, highlighting disruption of the vascular extracellular matrix (COL4A2, LOX, SH3PXD2A, GPR126, HTRA1), pericyte differentiation (FOXF2, GPR126), TGF-β signalling (HTRA1), and myelination (ULK4, GPR126) in disease risk." (PMID 33773637, 2021). "A few common examples of monogenetic abrasions that result in stroke are CADASIL (NOTCH-3 gene) and CARASIL (HTRA1)." (PMID 41164024, 2025). "Clinical phenotype frequencies varied widely: stroke, 9% (TREX1) to 52% (HTRA1 heterozygotes); cognitive features, 0% (ADA2) to 64% (HTRA1 homozygotes); and psychiatric features, 0% (COL4A2; ADA2) to 57% (CTSA)." (PMID 35699195, 2022).
gastric cancer (23 papers, 2012 to 2025). A primary or metastatic malignant neoplasm involving the stomach. "HtrA1 downregulation has also been observed to be associated with poor chemotherapy response in patients with gastric cancer." (PMID 26035313, 2015). "In addition, high HTRA1 expression has been associated with poor prognosis in gastric cancer patients." (PMID 38334007, 2024). "Studies have shown that HTRA1 expression is associated with immune cell infiltration and survival in breast cancer and promotes the transdifferentiation of normal fibroblasts into cancer-associated fibroblasts by activating the NF-κB/bFGF signaling pathway in gastric cancer." (PMID 39790460, 2025). "HtrA1 downregulation has also been connected to a poor chemotherapy response in patients with gastric cancer." (PMID 38609535, 2024). "According to the studies, overexpression of HtrA1 can significantly increase bFGF/FGF2 secretion by gastric cancer cells by activating NF-кB signal." (PMID 34563186, 2021). "As HtrA1 expression in gastric carcinoma cell line is up-graduated, α-SMA expression in normal fibroblasts will be increased." (PMID 34563186, 2021). "Mechanistically, HtrA1 inhibits gastric carcinoma cells, and weakened the effect of cell in proliferating, invading, and migrating." (PMID 34563186, 2021). "Decreased expression of HtrA1 has been reported in several cancers, including gastric cancer, breast cancer, and melanoma." (PMID 30484491, 2018). "Another study revealed that the protein levels of HtrA1 were lower in gastric cancer tissue than those in normal gastric tissue." (PMID 30484491, 2018). "Different investigations observed the downregulation of HTRA1 expression in various cancers types, such as melanoma, mesothelioma, lung, ovarian, bladder urothelial, breast, gallbladder and gastric cancer." (PMID 27809811, 2016). "Similar findings were observed in ovarian and gastric cancer patients where high HTRA1 levels correspond to the best response to cisplatin-based therapies." (PMID 26799320, 2016). "Expression levels of HtrA1 in patients with ovarian or gastric cancers correlated with their response rate to cisplatin-based treatment regimens." (PMID 22761798, 2012). "Fourth, positive, statistically significant relationships have been found between HtrA1 expression level and survival in patients with gastric cancer and mesothelioma." (PMID 22761798, 2012). "HtrA serine peptidase 1 (HTRA1), which is involved in malignant transformation of several cell types, is positively correlated with αSMA expression in gastric cancer tissue and induces the expression of αSMA in NFs through NFκB-mediated FGF-2 expression and export." (PMID 37046676, 2023). "It is predicted that when HtrA1 is detected before chemotherapy, platinum-based chemotherapy for gastric cancer may be needed." (PMID 34563186, 2021). "Therefore, epigenetic silencing of the HTRA1 gene enables the reactivation of HTRA1 gene expression in gastric carcinoma cells." (PMID 34563186, 2021). "Catalano and colleagues mainly assessed whether HtrA1 levels affect chemo-responsiveness in 80 patients with advanced gastric cancer." (PMID 26035313, 2015). "Interestingly, high HTRA1 expression is associated with shorter survival in renal and urothelial cancers, as evaluated by the Human Protein Atlas database; conversely, HTRA1 tends to be downregulated in the metastatic foci of melanoma and gastric cancer when compared to the primary tumor." (PMID 34202399, 2021). "Compared with the general issue, gastric cancer (GC) tissue expresses lower HtrA1." (PMID 34563186, 2021). "Catalano and colleagues investigated the chemo-responsiveness of gastric cancer in relation to HtrA1 levels in terms of OS and DFS, hypothesizing that the HtrA1 level may be used as predictor of responsiveness to chemotherapy." (PMID 26035313, 2015).
Alzheimer disease (17 papers, 2013 to 2025). A progressive, neurodegenerative disease characterized by loss of function and death of nerve cells in several areas of the brain leading to loss of cognitive function such as memory and language. "The PDZ serine protease HTRA1 degrades fibrillar tau, which is associated with Alzheimer’s disease, and inactivating mutations to mitochondrial HTRA2 are implicated in PD." (PMID 38499535, 2024). "The serine protease high-temperature requirement protein A1 (HtrA1) is associated with protein-misfolding disorders such as Alzheimer's disease and transforming growth factor β–induced protein (TGFBIp)–linked corneal dystrophy." (PMID 31197037, 2019). "The same group suggests that HTRA1 is implicated in Alzheimeŕs disease by degradation of amyloid β in the human brain, while the application of an HTRA1 inhibitor causes accumulation of amyloid β in astrocyte cells." (PMID 25329061, 2014). "The PDZ serine protease HTRA1 degrades fibrillar tau, which is associated with Alzheimer’s disease." (PMID 38499535, 2024). "HTRA1 is also highly expressed in the brain and has been implicated in Alzheimer’s disease." (PMID 34639128, 2021). "Htra3 is a gene involved in intracellular protein hydrolysis and a paralog of Htra1 and was identified as a biomarker for Alzheimer’s disease in mice through proteomic analysis." (PMID 39799000, 2024). "HtrA1 is a PDZ serine protease that degrades fibrillar tau, which is associated with Alzheimer disease (AD)." (PMID 37674720, 2023). "Htra1 is demonstrated to cleave Tau while Tau was proven to be the trigger and bullet in Alzheimer disease pathogenesis." (PMID 32338274, 2020). "ECM remodelling by HTRA1 affects a variety of pathobiological conditions such as osteoarthritis, cancer, and Alzheimer’s disease." (PMID 31315563, 2019). "HtrA1 appears to be involved in several physiological processes as well as in the pathogenesis of conditions such as Alzheimer’s disease and osteoarthritis." (PMID 26035313, 2015). "Though its exact role is not well understood, HTRA1 seems to be involved in several pathologies, as rheumatoid arthritis, osteoarthritis, Alzheimer’s disease, age-related macular degeneration and some types of cancer." (PMID 25329061, 2014). "HtrA1 has previously been shown to colocalize with the corneal amyloid associated with the V624M mutation in TGFBI and with β-amyloid plaques in Alzheimer disease." (PMID 23592924, 2013). "Furthermore, HtrA1 is demonstrated to degrade the aggregated and damaged tau, a protein that aggregates into intracellular neurofibrillary tangles in many neurological disorders such as Alzheimer’s disease." (PMID 34639128, 2021). "Elevated HTRA1 has been found not only in AMD, but also in age-related frailty and Alzheimer’s disease, two age-related diseases." (PMID 37316948, 2023).
breast carcinoma (16 papers, 2008 to 2025). "HTRA1 was upregulated on the SIN3B knockdown gene list and high HTRA1 expression is associated with overall and disease-free survival in patients with breast cancer." (PMID 27780928, 2016). "Downregulation of HtrA1 protein is associated with poor survival in mesothelioma, hepatocellular carcinoma and breast cancer; in the latter study node-positivity was associated with shorter survival." (PMID 26035313, 2015). "To evaluate a possible role of CpG-hypermethylation in causing HTRA1 downregulation in breast tumors, we subsequently analyzed a set of tumor specimens in addition to breast cancer cell lines by applying bisufite-sequencing techniques." (PMID 23580433, 2013). "HTRA1 downregulation was detected in more than 50% of the breast cancer specimens and was associated with higher tumor stage (p = 0.025)." (PMID 23580433, 2013). "HTRA1 levels are downregulated in pancreatic, gastric, prostate, lung, bladder, hepatocellular carcinoma, ovarian, and breast cancers and correlate with increased tumor growth, epithelial-mesenchymal transition (EMT), metastasis, and chemoresistance." (PMID 38474424, 2024). "Overexpression of HTRA1 inhibits the invasion and migration of melanoma and breast cancer cells, respectively." (PMID 38634469, 2024). "Analysis of HtrA1 levels in relation to overall survival and disease free survival in breast cancer indicated that patients with higher HtrA1 levels had a better prognosis." (PMID 29409460, 2018). "Here, we show downregulation of HTRA1 mRNA expression in a relevant number of breast cancers derived from a cohort of 131 early stage breast cancer patients, validated by public data sets of 2809 cases." (PMID 23580433, 2013). "In the present study, we have investigated the presence of HTRA1 transcripts in a panel of 131 breast cancer specimens by qPCR." (PMID 23580433, 2013). "HTRA1 is a highly conserved serine protease which has been implicated in suppression of epithelial-to-mesenchymal-transition (EMT) and cell motility in breast cancer." (PMID 23580433, 2013). "In contrast, low HTRA1 expression was previously shown to trigger EMT in breast cancer cells which is most likely involved in drug resistance." (PMID 23580433, 2013). "In our breast cancer patient cohort, we observed reduced HTRA1 expression levels particularly in patients exhibiting unfavorable clinical features such as high numbers of affected lymph nodes (≥4 lymph nodes)." (PMID 23580433, 2013). "Downregulation of HTRA1 was indeed shown to stimulate expression of mesenchymal markers and characteristics in breast cancer cells." (PMID 23580433, 2013). "Further investigation will be necessary to unravel the regulation of HTRA1 expression in breast cancer in order to stimulate re-expression of this tumor-suppressor for the purpose of clinical intervention, e.g, by HDAC inhibitors or demethylating agents." (PMID 23580433, 2013). "Two sets of six tumor samples displaying high and low expression of HTRA1, respectively, were chosen from breast cancer specimens of our study." (PMID 23580433, 2013). "We next examined HtrA1 transcript levels in 7 breast epithelial cell lines, including 5 human breast cancer (hBC) cell lines (MCF7, MDA-MB-231, MDA-MB-468, NM2C5, and M4A4), and 2 immortalized non-tumorigenic cell lines (MCF10A and MCF12A), by QPCR." (PMID 22761798, 2012). "These experimental findings provide empirical support for the prediction that HtrA1 would be epigenetically regulated in breast cancer cell lines." (PMID 22761798, 2012). "To investigate HtrA1 gene regulation in breast cancer, we characterized expression in primary breast tissues and seven human breast epithelial cell lines, including two non-tumorigenic cell lines." (PMID 22761798, 2012).
breast carcinoma (continued). "Herein, we illustrated a novel mechanism of PN-1 promoting breast cancer metastasis by binding and blocking HtrA1, which could cleave extracellular EGF and suppress cancer cell EMT." (PMID 31501409, 2019). "In breast cancer, lower HTRA1 expression levels were found to correlate with poor prognosis." (PMID 29269789, 2017). "Similarly, in a breast cancer study, HTRA1 was one among a panel of three markers which predicted response to doxorubicin-based chemotherapy." (PMID 23580433, 2013). "Thus, HTRA1 mRNA expression appears as a robust marker for breast cancer outcome supported by two different methodologies to assess transcript levels." (PMID 23580433, 2013). "With respect to the role of HTRA1 in EMT suppression, breast cancer patients with low HTRA1 expression might also be suited for drugs targeting EMT-related processes via inhibition of TGF-ß signaling." (PMID 23580433, 2013). "In promoter analyses, we in fact detected methylation of HTRA1 in a small subset of breast cancer specimens (two out of a series of 12), and in MCF-7 breast cancer cells which exhibited 22-fold lower HTRA1 mRNA expression levels compared to unmethylated MDA-MB-231 cells." (PMID 23580433, 2013). "Therefore, we evaluated the impact of HTRA1 mRNA expression on patient outcome using a cohort of 131 breast cancer patients as well as a validation cohort including 2809 publically available data sets." (PMID 23580433, 2013). "Targeting EMT-related processes downstream of HTRA1 might therefore proof an attractive new strategy in the treatment of breast cancer." (PMID 23580433, 2013). "HTRA1 mRNA expression levels in a cohort of 131 breast cancer patients." (PMID 23580433, 2013). "It would be of interest investigate HtrA1’s role in chronic oxidative stress, to determine whether there is therapeutic value in trying to restore its activity in breast cancer cells, since it is otherwise epigenetically silenced." (PMID 22761798, 2012). "Hence, the EGF/EGFR/PKC/MEK/ERK/EGR1/PN1/HtrA1 signaling axis might be a potential therapeutic target for breast cancer treatment." (PMID 31501409, 2019). "Finally, our data suggested that PN1 was a positive-feedback regulator of EGF signaling in breast cancer cells, which could block HtrA1 and prevent EGF cleavage, and EGF could then stimulate the metastatic spread of mammary tumors through induction of PN-1." (PMID 31501409, 2019). "Additionally, we analyzed two breast cancer cell lines showing different HTRA1 expression levels." (PMID 23580433, 2013). "Earlier studies have shown a down-regulation of HTRA1 in ovarian carcinoma and an up-regulation of the CA12 gene in breast carcinoma." (PMID 34062972, 2021). "We further investigated the underlying mechanisms of the activation of EGF signaling by PN-1 in breast cancer cells and demonstrated that PN-1 could prevent extracellular EGF proteolytic cleavage by HtrA1 through binding and blocking HtrA1." (PMID 31501409, 2019). "Evaluating the impact of HTRA1 expression on breast cancer outcome, we could show favorable survival (OS and DFS) in relation to high HTRA1 mRNA expression." (PMID 23580433, 2013). "Compared with these cells, MDA-MB-231 breast cancer cells displayed no detectable methylation accompanied by a 22-fold higher HTRA1 mRNA expression." (PMID 23580433, 2013). "HtrA1 staining was also reduced in all of the human breast cancer cell lines, compared with the normal tissue and non-tumorigenic cell line controls." (PMID 22761798, 2012). "In concordance, HtrA1 expression was significantly reduced in all of the breast cancer cell lines examined, compared with their non-tumorigenic counterparts." (PMID 22761798, 2012).
breast carcinoma (continued). "Similarly, we did not see any cases with pronounced HTRA1 mRNA expression in breast cancer samples displaying very high estrogen receptor values." (PMID 23580433, 2013).